CT70 (cancer/testis associated transcript 70)
Synonyms: LeXis
Gene: Long non-coding RNA gene on chromosome 9 (104,970,593 to 104,991,818, reverse strand). Ensembl gene ENSG00000230013.
Diseases named in the same sentence as CT70 in open-access papers:
CT70 is named in the same sentence as 12 diseases in open-access papers, as found by Europe PMC text mining. Sharing a sentence is not in itself a finding about the gene and the disease.
CT70 shares sentences with these, for which no sentence is quoted: atherosclerosis (5 papers); Hepatic steatosis (2); aortic atherosclerosis (1); Cholestatic liver disease (1); diabetes (1); familial hypercholesterolemia (1); hepatocellular carcinoma (1); hyperlipidemia (1); Hypertension (1); liver fibrosis (1); respiratory diseases (1); steatosis (1).